RNF26 (ring finger protein 26)
Description:
E3 ubiquitin-protein ligase that plays a key role in endosome organization by retaining vesicles in the perinuclear cloud. Acts as a platform for perinuclear positioning of the endosomal system by mediating ubiquitination of SQSTM1 through interaction with the ubiquitin conjugating enzyme UBE2J1. Ubiquitinated SQSTM1 attracts specific vesicle-associated adapters, forming a molecular bridge that restrains cognate vesicles in the perinuclear region and organizes the endosomal pathway for efficient cargo transport. Also acts as a regulator of type I interferon production in response to viral infection by mediating the formation of 'Lys-11'-linked polyubiquitin chains on TMEM173/STING, leading to stabilize TMEM173/STING. Also required to limit type I interferon response by promoting autophagic degradation of IRF3.
Synonyms: MGC2642
Tractability: Antibody: UniProt predicts a signal peptide or a membrane-spanning region. PROTAC: ubiquitination databases record sites on it.
Gene: Protein-coding gene on chromosome 11 (119,334,527 to 119,337,309, forward strand). Ensembl gene ENSG00000173456.
Subcellular location: Endoplasmic reticulum membrane
Subcellular location (Human Protein Atlas): Nucleoplasm; Cytosol; Vesicles
Gene Ontology:
Molecular function: protein binding; ubiquitin protein ligase activity; zinc ion binding
Biological process: endosome organization; negative regulation of defense response to virus; protein K11-linked ubiquitination; protein localization to perinuclear region of cytoplasm; protein ubiquitination; regulation of type I interferon production; ubiquitin-dependent protein catabolic process
Cellular component: endoplasmic reticulum membrane
Genetic constraint (gnomAD): Loss-of-function variants: 8 observed, 24.13 expected, observed/expected ratio (o/e) 0.33, 90% interval 0.19 to 0.6. The upper end of that interval is the gene's LOEUF score, 0.6, which puts it in group 2 of 6, group 1 being the genes least tolerant of losing a copy. Missense variants: 470 observed, 572.06 expected, observed/expected ratio (o/e) 0.82, 90% interval 0.76 to 0.89. Synonymous variants: 262 observed, 259.42 expected, observed/expected ratio (o/e) 1.01, 90% interval 0.91 to 1.12.
Homologues: Orthologues: chimpanzee RNF26 (99% identical), macaque RNF26 (98% identical), pig RNF26 (91% identical), rabbit RNF26 (90% identical), mouse Gm49380 (87% identical), mouse Rnf26 (87% identical), guinea pig RNF26 (86% identical), mouse Rnf26rt (86% identical), rat Rnf26 (85% identical), tropical clawed frog rnf26 (39% identical), zebrafish rnf26 (36% identical), Caenorhabditis elegans C56A3.4 (9% identical).